REST (RE1 silencing transcription factor)
Diseases named in the same sentence as REST in open-access papers (continued):
Sharing a sentence is not in itself a finding about the gene and the disease.
deafness (6 papers, 2019 to 2024). An inherited or acquired condition characterized by the complete loss of the ability to hear from one or both ears. "The mutation found in the gene REST in our cohort has been previously associated with other diseases, such as deafness and gingival fibromatosis." (PMID 39596629, 2024). "Previously, a deep intronic REST c.983-2247C>T variant has been demonstrated to cause dysregulation of alternative splicing and deafness and a gain-of-function has been suggested as a disease mechanism." (PMID 36509837, 2023). "In summary, our results demonstrate that REST is essential for hearing and its deficiency causes upregulation of Kv7.4 channels contributing to the dysfunction of SGNs and HCs and deafness in mice." (PMID 36125121, 2022). "Specifically, in humans, the deafness-causing DFNA27 mutation creates a reading frame-preserving version of exon 4 of REST by relocating the splice acceptor site of this exon." (PMID 33087486, 2020). "Proper splicing of exon 4 of REST mRNA requires SRRM4, and a mutation in the REST gene is associated with defective exon 4 splicing and deafness." (PMID 31162605, 2019). "To demonstrate that the upregulation of Kv7.4 channels caused by REST deficiency leads to deafness in mice, we investigated whether blocking Kv7.4 channels could rescue hearing loss in Rest cKO mice." (PMID 36125121, 2022). "Here, we set out to test whether the deafness of Srrm4bv/bv mice is related to the lack of REST inactivation in these animals." (PMID 33087486, 2020).
depression (5 papers, 2017 to 2024). "In summary, interaction analysis indicated that intergenic rs12128399, rs6660757 and variants in HPSE2, REST and from the 1p31.1 region (including ADGRL2) represent lifetime depression-dependent genetic factors for migraine." (PMID 34972135, 2021). "Expression of the NGF, BDNF, and REST genes at both protein and mRNA levels is lower in patients with depressive disorders than in the control group." (PMID 33804468, 2021). "Expression of NGF, BDNF, and REST genes at both protein and mRNA levels was lower in patients with depressive disorders than in the control group." (PMID 33804468, 2021). "Furthermore, results allowed the separation of variants that play a role in migraine accompanied by depression, like ADGRL2, REST and HPSE2, from those that play a general role in migraine, like PRDM16." (PMID 34972135, 2021). "In contrast, intergenic rs6660757 and rs12128399, rs1889974 in HPSE2, rs11163394 in ADGRL2 and rs1043215 of REST may only serve as biomarkers in migraine accompanied by lifetime depression." (PMID 34972135, 2021). "Furthermore, this study also provides evidence that SNPs of the previously identified migraine risk genes REST, ADGRL2, HPSE2 and 1p31.1 show lifetime depression-dependent associations with the disease." (PMID 34972135, 2021). "In fact, aberrant REST transcriptional regulation was shown in patients with major depressive disorder in current depressive state, but not in remission." (PMID 34972135, 2021). "While the p31.1 region and PRDM16 are worthy of further investigations in migraine in general, REST, HPSE2 and ADGRL2 may be prime candidates behind migraine pathophysiology in patients with comorbid depression." (PMID 34972135, 2021). "Bayesian relevance analysis confirmed the relevance of intergenic rs6660757 and rs12128399 (p31.1), rs1043215 (REST), rs1889974 (HPSE2) and rs11163394 (ADGRL2) from depression interaction results, and the moderate relevance of rs77864828 and rs2455107 of PRDM16 from main effect analysis." (PMID 34972135, 2021). "They found decreased REST mRNA expression and increased mRNA expression of CRH, adenylate cyclase 5 and the tumor necrosis factor superfamily in patients with major depressive disorder during an acute episode but not in remission." (PMID 33804468, 2021).
gingival fibromatosis (5 papers, 2021 to 2025). "We review the clinical data from all previously published patients with Jones syndrome and previously published patients with pathogenic REST variants associated with gingival fibromatosis or sensorineural hearing loss." (PMID 36509837, 2023). "To date, genetic variants in five genes, SOS1, REST, ZNF862, ALK, and CD36, have been linked to hereditary gingival fibromatosis." (PMID 39201553, 2024).
Hyperglycemia (5 papers, 2012 to 2023). An increased concentration of glucose in the blood. "In a separate study, using an inducible REST transgene under the control of the Pdx1 promoter, we also observed postnatal beta cell loss leading to hyperglycemia (unpublished data)." (PMID 23029270, 2012). "In diabetic RIP-REST mice, high levels of REST were associated with postnatal beta cell apoptosis, which resulted in gradual beta cell loss and sustained hyperglycemia in adults." (PMID 23029270, 2012). "Aberrant induction of REST expression in neurons or progenitors plays a role in neurodegenerative and neurodevelopmental diseases, while reactivation of REST in adult mouse β-cells leads to their dedifferentiation and hyperglycemia." (PMID 33921851, 2021). "Aberrant induction of REST expression in neurons or progenitors plays a role in neurodegenerative and neurodevelopmental diseases while reactivation of REST in adult mice β-cells leads to their dedifferentiation and hyperglycemia." (PMID 31817798, 2019).
lung carcinoma (5 papers, 2019 to 2023). "REST is a potential marker for the diagnosis of lung cancer types and a potential target for the treatment of some types of lung cancers." (PMID 37892159, 2023). "The regulation pattern of REST varies in different types of lung cancers." (PMID 37892159, 2023). "Altogether, these experiments identify conserved roles for REST and YAP in Notch-driven inhibition of the neuroendocrine cell fate in embryonic lungs, adult lungs, and lung cancer." (PMID 35577801, 2022). "Moreover, in lung cancer cells, the nucleus-localized USP15 can deubiquitylate histone H2B and inhibit degradation of the RE1-silencing transcription factor (REST) on the ribosome, which plays a pivotal role in cell cycle oscillations." (PMID 34177595, 2021). "Studies suggest a strong link between REST and CREB in neuronal and lung cancer cells, but no studies have previously shown that CREB activation plays a role in the upregulation of EAAT2 by REST." (PMID 34756885, 2021).
prostate adenocarcinoma (5 papers, 2015 to 2025). "Loss of REST is a key factor for prostate adenocarcinoma cells to gain NE phenotypes under various conditions, including AR inhibition." (PMID 29156689, 2017). "Lastly, RNAseq profiling in matched NePC and prostate adenocarcinomas showed downregulation of the transcriptional complex REST, which is integral to the repression of neuronal differentiation." (PMID 26444865, 2015). "By binding SLC9A3R1 to activate autophagy and destabilize REST, OPRK1 reprograms prostate adenocarcinoma cells toward a NE lineage, thereby fueling ARPI resistance." (PMID 41353213, 2025). "EZH2 and REST clearly have opposite functions and expression patterns in NEPC compared to prostate adenocarcinoma." (PMID 38777812, 2024). "In prostate adenocarcinoma cells, we observed that short-term REST knock-down led to an increase of BAF53B (ACTL6B) mRNA and protein levels, but the effect was modest, while other neuronal genes known to be negatively controlled by REST (e.g., synaptophysin) were highly upregulated." (PMID 33144576, 2020).
prostate tumor (5 papers, 2015 to 2024). "Reduction of active REST by SRRM4-driven splicing has been shown to promote a NE phenotype in prostate tumors." (PMID 39080761, 2024). "REST-binding sites were found on 28 of 50 transcriptionally active genes in NEPC and in vivo in a cohort of 218 prostate tumors, in which REST downregulation was observed in 50% of NEPC tumors." (PMID 25699233, 2015). "Downregulation of REST can be detected in approximately 50% of NE prostate tumors." (PMID 38673756, 2024). "Overexpression of REST, on the contrary, downregulates the epithelial–mesenchymal transition (EMT), resulting in increased migration and invasiveness of prostate tumor cells." (PMID 38673756, 2024).
Seizure (5 papers, 2016 to 2024). A seizure is an intermittent abnormality of nervous system physiology characterized by a transient occurrence of signs and/or symptoms due to abnormal excessive or synchronous neuronal activity in the brain. "To further examine whether altered Cl- concentrations could cause this susceptibility to PTZ-induced seizure, we investigated the expression of Nkcc1 and Kcc2, the latter being transcriptionally regulated by Srrm4 through its downstream transcription factor REST." (PMID 38229888, 2024).
triple-negative breast carcinoma (5 papers, 2017 to 2025). An invasive breast carcinoma which is negative for expression of estrogen receptor (ER), progesterone receptor (PR), and human epidermal growth factor receptor 2 (HER2). "Subsequent experiments essentially relied on SCYL1HSS126244, which was shown to affect REST protein expression levels and delay REST turnover in Hek293T cells and triple-negative breast cancer cell lines." (PMID 28570664, 2017). "A recent study identified SCYL1 as one of the components of the oncogenic STP axis, which promotes triple-negative breast cancer by regulating degradation of the REST tumor suppressor." (PMID 28570664, 2017). "Our studies, however, do not contest the possible role of Tex14 in mediating REST turnover; the formation of an STP complex; or the possibility of SCYL1, Tex14, PLK1, and REST being aberrantly expressed in triple-negative breast cancer cells." (PMID 28570664, 2017). "In addition, a genetic screening of triple-negative breast cancer subtype (TNBC) demonstrated the presence of STP axis components (SCYL1, TEX14, and PLK1) which degraded the REST by phosphorylating a conserved REST phospho-degron and associated the REST interaction with ubiquitin-ligase β-TrCP." (PMID 40006989, 2025). "Among REST, CTCF, and CEBPB, CEBPB is the only member that was significantly enriched in C19MChigh group (REST and CTCF data were not shown) and hence we investigated whether CEBPB is functional in triple negative breast cancers." (PMID 30335837, 2018).
autism (4 papers, 2015 to 2023). Persistent deficits in social interaction and communication and interaction as well as a markedly restricted repertoire of activity and interest as well as repetitive patterns of behavior. "Genes regulated by REST/NRSF regulate multifaceted neuronal phenotypes, and their defects in the machinery cause neuropathies, disorders of neuron activity), autism and so on." (PMID 33652591, 2021). "To examine the protein level of the RNAseq results in mouse CAD cells, we tested genes involved in autism risk (NLGN1), neurodegeneration (ATXN1), neurogenesis (REST), embryonic development (TLE4), and neuronal migration (KIF1A)." (PMID 26094033, 2015). "Thus, the correct induction of CTNND2 expression through the reduction of REST and TRIM28 may be crucial for normal neuronal development and the prevention of autism, and TRIM28 may be involved in the regulation of CTNND2 by acting as a corepressor of REST." (PMID 27976729, 2016).
brain cancer (4 papers, 2014 to 2023). A primary or metastatic malignant neoplasm affecting the brain. "The final section of this review, dealing with therapies, was short, concerning brain cancers, such as those treated with already known drugs or exposed to REST associated with various complexes." (PMID 31905747, 2019). "The role of REST in the proliferation of brain cancer cells, previously investigated in only a few cases, has expanded recently." (PMID 31905747, 2019). "REST was found to bind proximally to many of the well-characterized neuronal genes in various brain cancer cell lines: PFSK-1, SK-N-SH, U87 and in H1-derived neurons, a phenomenon previously reported." (PMID 24922058, 2014). "REST has been found aberrantly expressed in brain cancer and other cancer types." (PMID 37301955, 2023). "Similarly, REST expression was also higher in brain cancer compared to normal tissues." (PMID 37170124, 2023).
cardiac hypertrophy (4 papers, 2012 to 2025). "Regulation of this gene by REST is a major pathway in cardiac hypertrophy: loss of REST expression in diseased heart allows the re-activation of the fetal cardiac gene expression program and resultant hypertrophy." (PMID 22496669, 2012). "Their study identified a novel signaling pathway for pathological cardiac hypertrophy: m6A-circCDYL-tCDYL-100-REST (RE1-silencing transcription factor)/CDYL-RhoA (Ras homolog family member A)/BNP (brain natriuretic peptide)." (PMID 41181701, 2025). "The mouse model induced by intraperitoneal injection of Ang II showed significant cardiac hypertrophy and dysfunction, but the mRNA and protein levels of REST were found to be significantly down-regulated in the hypertrophic heart tissue." (PMID 39157454, 2024). "Hereby, REST alleviates inflammation response in cardiac hypertrophy via triggering NF-κB and JAK/STAT pathways." (PMID 39157454, 2024). "REST has been proven to exert a role in regulating inflammatory responses in the nervous system, we hence try to understand whether REST mediates inflammation pathways involved in cardiac hypertrophy." (PMID 39157454, 2024). "REST deficiency up-regulated UCHL1 expression, which then exacerbated cardiac hypertrophy." (PMID 39157454, 2024). "Similarly, the transverse aortic constriction (TAC) model with cardiac hypertrophy and heart dysfunction also exhibited an obvious decrease in REST expression level." (PMID 39157454, 2024). "Overall, these in vivo and in vitro data suggested that REST might play a potential role in the regulation of cardiac hypertrophy." (PMID 39157454, 2024). "Moreover, the STAT3 pathway, which can regulate inflammation and fibrosis in cardiac hypertrophy, and JAK2 were further activated in the absence of REST in TAC mice." (PMID 39157454, 2024).
colorectal cancer (4 papers, 2022 to 2025). A primary or metastatic malignant neoplasm that affects the colon or rectum. "An array-comparative genomic hybridization (CGH) analysis in colorectal cancer revealed that REST is a frequent target of deletion in colorectal cancer (CRC)." (PMID 40006989, 2025). "SNP rs2228991 in REST, a gene in non-neuronal tissues encoding a transcription factor binding to the silencer of neuronal genes, was reported to be associated with an increased risk of colorectal cancer when combined with SNPs in the NFKB1 gene." (PMID 36292186, 2022).
dementia with Lewy bodies (4 papers, 2017 to 2022). "Dysregulation of REST has been documented in AD, FTD, and dementia with Lewy bodies, and elevated levels of REST are associated with the preservation of cognition." (PMID 34720873, 2021). "REST was sequestrated in Lewy bodies and cytosol, resulting in the absence or low REST levels in the nucleus of PD and dementia with Lewy body patients." (PMID 34756885, 2021). "Growing evidence shows that REST is neuroprotective, and its dysfunction may contribute to the neuropathology of multiple neurological disorders, such as PD, dementia with Lewy body, and AD." (PMID 34756885, 2021).
fibroid (4 papers, 2022 to 2026). "The combined loss of both PRICKLE1 and REST in leiomyomas and the mislocalization of REST in leiomyoma cells point to a direct role for PRICKLE1 in the loss of REST in uterine fibroids." (PMID 39314474, 2024). "We examined the regulation of known REST interacting proteins in leiomyomas in a candidate gene approach to identify the mechanism for the loss of REST in leiomyomas." (PMID 39314474, 2024). "Taken together, our results provide a novel mechanism for the loss of REST and identify potential targets for the development of treatment for fibroids in the future." (PMID 39314474, 2024). "Taken together, we identify a novel pathway that connects environmental estrogen exposure, suppression of PRICKLE1, loss of REST-dependent epigenetic control, and aberrant gene expression in leiomyomas." (PMID 39314474, 2024). "Our research on the role of REST in uterine fibroids indicated that the loss of REST alters steroid hormone response in the uterus (unpublished data)." (PMID 35177031, 2022). "In addition to GPR10, many of the most aberrantly expressed genes in leiomyomas are direct targets of REST, indicating that the loss of REST has an important role in downstream epigenetic changes leading to leiomyoma development and growth." (PMID 39314474, 2024). "Further, REST protein showed predominant cytoplasmic localization in leiomyomas, suggesting that the loss of these protein partners may be linked." (PMID 39314474, 2024). "The involvement of REST in these interconnected pathways highlights its crucial role in maintaining cellular homeostasis and its potential as a therapeutic target in fibroid treatment." (PMID 41601477, 2026). "In an effort to identify the mechanism of loss of REST in leiomyoma, we focused on PRICKLE1, a WNT/PCP protein that associates with REST." (PMID 39314474, 2024). "Crucially, mice exposed neonatally to environmental estrogens, proven risk factors for fibroids, expressed lower levels of PRICKLE1 and REST in the myometrium." (PMID 39314474, 2024). "Intriguingly, despite normal β-TRCP levels in both myometrial smooth muscle cells (MSMCs) and leiomyoma smooth muscle cells (LSMCs), REST is degraded at a faster rate in cultured leiomyoma cells compared to normal myometrial cells." (PMID 39314474, 2024). "Our results support a novel ERα/ EZH2 – PRICKLE1 mediated, REST- target-specific gene derepression model in the pathogenesis of leiomyomas." (PMID 39314474, 2024). "Collectively, our results identify a novel link between estrogen exposure and PRICKLE1/REST-regulated tumorigenic pathways in leiomyomas." (PMID 39314474, 2024). "Relevant to the role of PRICKLE1 in regulating the stability of REST without affecting its mRNA expression, we had shown earlier that the loss of REST protein expression in leiomyomas does not accompany a corresponding decline in its mRNA expression." (PMID 39314474, 2024). "How the missense mutations to MED12 reported in leiomyoma affect PRICKLE1 and the WNT/PCP pathway, in addition to REST localization and function are currently unknown." (PMID 39314474, 2024). "Interestingly, in leiomyomas the REST mRNA level is unchanged in comparison to healthy myometrium, indicating that REST expression is regulated post-transcriptionally." (PMID 39314474, 2024). "Given the widespread loss of REST and the relatively normal levels of β-TRCP expression in leiomyomas, we hypothesized that alternative mechanisms exist for the functional loss of REST in leiomyoma cells." (PMID 39314474, 2024). "Because REST is a major epigenetic regulator of long-term gene repression in the periphery, we hypothesized that environmental estrogens may promote the development of leiomyomas by lowering REST levels and thereby impairing its function in the myometrium." (PMID 39314474, 2024). "PRICKLE1 expression is markedly lower in leiomyomas, and the suppression of PRICKLE1 significantly down regulates REST protein levels." (PMID 39314474, 2024).